LMO7 (LIM domain 7)
Synonyms: FBX20; FBXO20; KIAA0858; LMO7b; LOMP
Tractability: PROTAC: UniProt records ubiquitination sites on it; ubiquitination databases record sites on it; its protein half-life has been measured.
Gene: Protein-coding gene on chromosome 13 (75,620,434 to 75,859,870, forward strand). Ensembl gene ENSG00000136153.
Subcellular location (Human Protein Atlas): Actin filaments; Cytosol
Pathways (Reactome):
Disease: Signaling by ALK fusions and activated point mutants
Immune System: Antigen processing: Ubiquitination & Proteasome degradation
Metabolism of proteins: Neddylation
Gene Ontology:
Molecular function: protein binding; ubiquitin-protein transferase activity
Biological process: positive regulation of transcription by RNA polymerase II; protein ubiquitination; SCF-dependent proteasomal ubiquitin-dependent protein catabolic process; regulation of cell adhesion; regulation of signaling
Cellular component: actin cytoskeleton; cell surface; cytoplasm; focal adhesion; mitochondrion; nuclear envelope; nucleus; apical plasma membrane; cytosol; SCF ubiquitin ligase complex; ubiquitin ligase complex
Genetic constraint (gnomAD): Loss-of-function variants: 73 observed, 137.68 expected, observed/expected ratio (o/e) 0.53, 90% interval 0.44 to 0.64. The upper end of that interval is the gene's LOEUF score, 0.64, which puts it in group 2 of 6, group 1 being the genes least tolerant of losing a copy. Missense variants: 1,526 observed, 1,582.7 expected, observed/expected ratio (o/e) 0.96, 90% interval 0.92 to 1.01. Synonymous variants: 563 observed, 564.04 expected, observed/expected ratio (o/e) 1, 90% interval 0.93 to 1.07.
Homologues: Orthologues: chimpanzee LMO7 (99% identical), macaque LMO7 (97% identical), dog LMO7 (85% identical), mouse Lmo7 (81% identical), rat Lmo7 (81% identical), rabbit LMO7 (77% identical), pig LMO7 (68% identical), tropical clawed frog lmo7 (46% identical), zebrafish lmo7a (39% identical), guinea pig Lmo7 (26% identical), zebrafish lmo7b (24% identical), Caenorhabditis elegans lim-8 (14% identical). Paralogues in human: LIMCH1 (21% identical).
Diseases named in the same sentence as LMO7 in open-access papers:
LMO7 is named in the same sentence as 42 diseases in open-access papers, as found by Europe PMC text mining. Sharing a sentence is not in itself a finding about the gene and the disease. The quoted sentences say what the papers report.
lung carcinoma (20 papers, 2015 to 2026). "An association between the deficiency of LMO7 and genetic predisposition to lung cancer has also been reported." (PMID 34827193, 2021). "LMO7 participates in cytoskeletal reorganization during carcinogenesis, and its downregulation in lung cancer is associated with poorer patient prognosis." (PMID 33671634, 2021). "LMO7 which regulates the actin cytoskeleton and adherens junctions, was described to be downregulated in malignant lung tissue, and LMO7 deficiency was found associated with genetic predisposition to lung cancer." (PMID 34827193, 2021). "In lung cancers, it functions as a tumour suppressor molecule while a shortage of LMO7 confers a genetic predisposition to lung cancer." (PMID 35127511, 2021). "In lung cancer, LMO7 functions as a tumour suppressor and its deficiency confers a genetic predisposition to lung cancer." (PMID 28026121, 2017). "Exosomal miR-96-5p has been shown to increase cisplatin resistance in lung cancer cells possibly regulating LMO7 expression." (PMID 38065937, 2023). "Through a comparison of cancer tissue samples and adjacent normal tissue samples, we found that both AL137782.1 and LMO7 were expressed at higher levels in normal cells than in two types of lung cancers, LUAD and LUSC." (PMID 37762205, 2023). "Wnt3a/β-catenin, circSATB2, HIF-1α/COX-2, KLF9, and LMO7 in tumor-derived exosomes regulate genes or signaling pathways to promote proliferation and migration of lung cancer cells." (PMID 34511114, 2021). "EV-derived miR-96 has also been shown to promote lung cancer cell proliferation and migration by targeting LIM-domain-only protein 7 (LMO7)." (PMID 33472665, 2021). "Exosomal microRNA-96 (miRNA-96) fosters lung cancer progression by suppressing the activity of Lim domain 7 (LMO7) protein." (PMID 35127511, 2021). "MiR-96 mainly acts by targeting LIM-domain only protein 7 (LMO7) protein that helps in maintaining alveolar architecture, actin cytoskeleton and functions as tumor suppressor in lung cancer." (PMID 32641036, 2020). "A decreasing level of LMO7 was also seen in high‐grade lung cancer and lymph node with metastatic tumours." (PMID 28026121, 2017). "LMO7 expression was inversely correlated with lung cancer grades, and LMO7 overexpression reversed promoting effect of miR‐96." (PMID 28026121, 2017). "This is consistent with previous results that low LMO7 level was correlated with a poor prognosis of lung cancer patients." (PMID 28026121, 2017). "LMO7 possesses seed‐matching sites with miR‐96 at 3′‐UTR, and we showed that LMO7 overexpression and miR‐96 counteracted each other in lung cancer." (PMID 28026121, 2017). "Contrary to the tumour‐promoting role of miR‐96, LMO7 is a tumour suppressor of lung cancer, as demonstrated in our qPCR analysis that showed a decreased level of LMO7 in lung cancer patients." (PMID 28026121, 2017). "Lower LMO7 expression was seen in lung cancer than normal tissues and relatively lower LMO7 expression was seen in cancer tissue with higher grades and metastatic lymph node tissues." (PMID 28026121, 2017). "LMO7, a zinc-binding protein thought to have tumor suppressor activity in lung cancer, was the only commonly differentially expressed protein higher in ADC." (PMID 26539827, 2015). "The increased levels of miR-96 in both the tumor tissue and serum of lung cancer patients, along with the decreased level of LMO7 in tumor tissue, support the notion that miR-96 may play a tumor-promoting role in lung cancer." (PMID 38002256, 2023). "Furthermore, circulating exosomal miRNA-96 enhances cell migration and proliferation in lung cancer through the LIM-domain only protein 7 (LMO7) pathway." (PMID 34292880, 2021). "We also confirmed that LMO7 is down‐regulated in lung cancer." (PMID 28026121, 2017). "LMO7 is a target of miR‐96, and overexpression of LMO7 could reverse the promoting effect of miR‐96 in lung cancer." (PMID 28026121, 2017).
lung carcinoma (continued). "Furthermore, exosomal miR-96 promoted lung cancer progression by targeting LMO7." (PMID 33727921, 2021). "They concluded that circulating exosomal miR-96 played a promotive role in lung cancer cell proliferation and migration by targeting LIM-domain-only protein 7 (LMO7) and that treatment with a miR-96 inhibitor or the overexpression of LMO7 could reverse this promotive action." (PMID 31728212, 2019). "However, mechanism regulating LMO7 expression in lung cancer is still yet to be understood." (PMID 28026121, 2017). "In patient datasets, lower LMO7 expression and higher MGMT expression correlate with shorter overall survival in lung cancer (Kaplan-Meier Plotter analysis, p < 0.01)." (PMID 41763308, 2026). "Taking lung cancer as an example, miR-96-containing exosomes secreted from H1299 cells were demonstrated to exhibit oncogenic activity toward upregulated cell proliferation by directly targeting the production of the LIM-domain only protein 7 (LMO7) expression." (PMID 33805515, 2021).
breast carcinoma (8 papers, 2002 to 2022). "It has been reported that LMO7 played a role in the regulation of cell adhesion, mitosis, and cancer metastasis and progression, including breast cancer, lung adenocarcinoma, and pancreatic cancer." (PMID 35046938, 2021). "Although not reported in prostate cancer, reduced LMO7 expression inhibits breast cancer cell migration, and the LMO7-BRAF fusion frequently occurs in papillary thyroid cancer." (PMID 33671634, 2021). "Using transwell migration assays, they demonstrated that LMO7 knockdown markedly reduced the migration of MDA-MB-231 breast cancer cells by specifically regulating MRTF in a cell-specific manner." (PMID 33763427, 2021). "LMO7, also amplified in our samples, was shown to mediate cell-specific activation of Rho-MRTF_SRF pathway, where it plays an important role in breast cancer cells migration." (PMID 22879877, 2012). "Specifically, Hu and colleagues reported that the knockdown of LMO7 gene in the breast cancer cell line MDA-MB-231 could impair cell migration." (PMID 36303815, 2022). "Besides that, LMO7 significantly upregulated in invasive breast cancer cells, and it can regulate cell migration through mediating the activation of Rho-MRTF-SRF signaling pathway." (PMID 30546056, 2018). "LMO7 in gastric cancer has not been dealt with in any reports, but another isoform, LMO4 (a transcriptional regulator) inhibits differentiation of mammary epithelial cells in vitro and is overexpressed in breast cancers." (PMID 12402156, 2002).
Emery-Dreifuss muscular dystrophy (7 papers, 2010 to 2025). Emery-Dreifuss muscular dystrophy (EDMD) is characterized by muscular weakness and atrophy, with early joint contractures and cardiomyopathy. "LMO7 directly interacts with the nuclear membrane protein Emerin and may be associated with Emery Dreifuss muscular dystrophy (EDMD)." (PMID 34576220, 2021). "To test this, we analyzed RNA-Seq datasets, finding novel isoforms or isoform tissue-specificity for: Lap2, linked to cardiomyopathy; Nesprin 2, linked to Emery-Dreifuss muscular dystrophy and Lmo7, that regulates the Emery-Dreifuss muscular dystrophy linked emerin gene." (PMID 29912636, 2018). "Lmo7 – Emerin is an INM protein, that binds both lamin A and the BAF complex and is frequently mutated in Emery-Dreifuss muscular dystrophy." (PMID 29912636, 2018). "How might p130Cas-dependent focal adhesion regulation of Lmo7 relate to Emery-Dreifuss muscular dystrophy (EDMD)?" (PMID 24010014, 2013).
lung adenocarcinoma (7 papers, 2021 to 2025). A carcinoma that arises from the lung and is characterized by the presence of malignant glandular epithelial cells. "An animal study showed that LMO7‐deficient mice developed irregular and protruding epithelial lesions in the terminal and respiratory bronchioles at a young age, and these mice were susceptible to lung adenocarcinoma at an older age." (PMID 39023413, 2024). "Research has indicated an inverse relationship between LMO7 expression and the progression as well as prognosis of human lung adenocarcinoma." (PMID 41318472, 2025). "LIM-domain only protein 7 (LMO7), also significantly downregulated in AA-exposed colon, has been suggested to act as a tumor suppressor for murine lung adenocarcinoma." (PMID 37888706, 2023). "Analysis of the clinical correlation between LMO7 expression and lung adenocarcinoma (LUAD) patients showed that LMO7 expression was negatively associated with lymphatic metastasis and poor prognosis." (PMID 37894409, 2023). "FBXO20 (LMO7) was downregulated in lung adenocarcinoma and relevant in tumor size, nodal involvement, and pathological stage as well as with a poor prognosis." (PMID 35046938, 2021). "In LRIG1-positive non-small cell lung cancer, LMO7 was a negative prognostic marker, while another study of lung adenocarcinoma showed that the loss of LMO7 was associated with a worse prognosis." (PMID 38918827, 2024). "Finally, Lmo7-deficient mice develop irregular epithelial lesions, which results in the development of lung adenocarcinoma at an older age, suggesting a role for Lmo7 as a tumor-suppressor gene." (PMID 34681951, 2021).
deafness (5 papers, 2020 to 2023). An inherited or acquired condition characterized by the complete loss of the ability to hear from one or both ears. "Lmo7-deficient knockout mice exhibited decreased density of filamentous actin, thinning of the cuticula, and hair cell deformities along with progressive hearing loss leading to profound deafness." (PMID 34847940, 2021). "There were 18 genes linked only to Metabolic hearing loss (including four deafness genes: DMD, DUOX2, CELSR1 and ELMO3) and 54 genes linked only to Sensory hearing loss (including four deafness genes: ARHGAP21, LMO7, UBE3B and ADGRV1)." (PMID 38011198, 2023). "PKHD1L1, DUOX2, CELSR1, ELMO3, ARHGAP21, LMO7 and UBE3B are all defined as deafness genes through work on the mouse orthologues." (PMID 37163093, 2023).
pancreatic cancer (5 papers, 2021 to 2025). "Loss of LMO7 function can induce cycle arrest and apoptosis of pancreatic cancer cells, making LMO7 has become a promising target for pancreatic cancer therapy." (PMID 40241795, 2025). "In addition, LMO7 is closely related to the progression and metastasis of pancreatic cancer." (PMID 40241795, 2025).
prostate carcinoma (4 papers, 2017 to 2021). A carcinoma that arises from epithelial cells of the prostate gland. "In cancer tissue, increased expression of LMO7 has been reported in colorectal, breast, liver, lung pancreas, stomach and prostate cancers, suggesting that an important role of LMO7 in cytoskeletal reorganization during carcinogenesis." (PMID 28026121, 2017). "In addition, the increased expression of Lmo7 has been reported in colorectal, breast, liver, lung, pancreas, stomach, and prostate cancer, suggesting that Lmo7 may play a role in carcinogenesis." (PMID 34681951, 2021).
gastric cancer (2 papers, 2002 to 2022). A primary or metastatic malignant neoplasm involving the stomach. "Circ_0008259, derived from LMO7 pre-mRNA, is highly expressed in gastric cancer, promoting the proliferation, motility, and regulating the glutamine metabolism of gastric cancer cells by “sponging” miR-30a-3p." (PMID 35813866, 2022).
hearing loss (2 papers, 2019 to 2022). "LMO7 colocalizes with eQTLs for the gene in GTEx skeletal muscle and SPTBN1 in thyroid tissue, such that decreased expression of these genes is correlated with increased risk for hearing loss in humans." (PMID 35661827, 2022).
metastatic tumors (2 papers, 2017 to 2021). "Together, these results indicate that LMO7 mRNA and protein expression is consistently increased in human and mouse primary and metastatic tumors, suggesting their positive correlation with PC progression." (PMID 33763427, 2021).
pancreatic ductal adenocarcinoma (2 papers, 2021 to 2025). An infiltrating adenocarcinoma that arises from the epithelial cells of the pancreas. "In pancreatic ductal carcinoma, LMO7 is reported to regulate the T cell differentiation and chemotaxis and thus achieve the immune escape." (PMID 41318472, 2025). "In freshly harvested human pancreatic ductal adenocarcinoma (PDAC) and pancreatic neuroendocrine tumors (PNETs), we detected the enhanced LMO7 production in human PDACs and PNETs with IHC and Western blot." (PMID 33763427, 2021).
Ascites (1 paper, 2021). Accumulation of fluid in the peritoneal cavity (between the layers of the peritoneum that lines the abdomen). "After inoculation of the distinct cells with or without LMO7 knockdown and knockout, the development of ascites and impairment of gait and breathing were daily observed which is used to define the humane endpoint of the resultant tumor-bearing mice." (PMID 33763427, 2021).
asthma (1 paper, 2020). "In addition, other identified genes were LRRC48 and CETN2 in asthma-COPD, COL15A1, GIMAP6, and JAM2 in asthma-IPF, along with LMO7, TSPAN13, LAMA3, and ANXA3 in COPD-IPF." (PMID 31952466, 2020). "These genes included RBM42, STX5, and TRIM41 in asthma, CYP27A1, GM2A, LGALS9, SPI1, and NLRC4 in COPD, ATF3, PPP1R15A, ZFP36, SOCS3, NAMPT, and GADD45B in IPF, LRRC48 and CETN2 in asthma-COPD, COL15A1, GIMAP6, and JAM2 in asthma-IPF and LMO7, TSPAN13, LAMA3, and ANXA3 in COPD-IPF." (PMID 31952466, 2020).
colorectal cancer (1 paper, 2018). A primary or metastatic malignant neoplasm that affects the colon or rectum. "Despite the role of ARL8A in colorectal cancer was rarely reported, LMO7 had been manifested dysregulation in human cancers." (PMID 30546056, 2018).
colorectal tumor (1 paper, 2018). "For such phenomenon, we speculated that, despite involved in colorectal tumor metastasis, LMO7 may not be a risk factor from the view of population level." (PMID 30546056, 2018).
Corneal astigmatism (1 paper, 2018). "In addition, LMO7 has been suggestively (P = 4 × 10−6 for rs11841001) associated with corneal astigmatism." (PMID 29449654, 2018).
glioblastoma (1 paper, 2025). The most malignant astrocytic tumor (WHO grade IV). "Among which, CDC73, PSMC2, SOCS3, and ETV4 were substantially upregulated; whereas PLK2 and LMO7 were substantially downregulated in glioblastoma cells than that in control." (PMID 41318472, 2025).
inflammatory bowel disease (1 paper, 2025). A spectrum of small and large bowel inflammatory diseases of unknown etiology. "There is a lack of research on the role of LMO7 in tumor immunity; however, a recent study on inflammatory bowel disease suggested that LMO7 could be detected in macrophages and was involved in macrophage activation." (PMID 39143228, 2025).
invasive breast carcinoma (1 paper, 2022). A carcinoma that infiltrates the breast parenchyma. "In the same study, the upregulation of LMO7 was also found in the stroma of invasive breast carcinoma, which presumably correlated with the expression of serum response factors that regulate muscle and actin cytoskeleton functions." (PMID 36303815, 2022).
laminopathies (1 paper, 2012). "We examined the effect of mutant TMEM43 on mRNA expression of four genes, LMO7, KCTD12, MBNL2 and RAP2A, located on chromosome 13, that have been shown to have abnormal expression in the setting of laminopathies with striated muscle dysfunction." (PMID 22458570, 2012).
osteosarcoma (1 paper, 2023). A usually aggressive malignant bone-forming mesenchymal neoplasm, predominantly affecting adolescents and young adults. "These differential splicing events, such as ES in the LMO7 and SLC37A4 loci, were further defined as osteosarcoma‐specific AS events." (PMID 37457661, 2023).
renal fibrosis (1 paper, 2022). A final common manifestation of a wide variety of chronic kidney diseases characterized by glomerulosclerosis and tubulointerstitial fibrosis. "LMO7 expression was reported to be upregulated in podocytes and myofibroblasts in mouse kidneys by gene expression profiling in renal fibrosis and podocytopathies." (PMID 36497072, 2022).
retinal degeneration (1 paper, 2017). Degeneration of the retina. "They include genes involved in nuclear trafficking and gene silencing (IPO8), fast axonal guidance and synaptic specificity (PCDH12), transduction of nerve signals (NRSN1), retinal degeneration (LMO7), synaptic glutamate release (SH3GL2), and broader nervous system development and function." (PMID 29064472, 2017).
tuberculosis (1 paper, 2024). A chronic, recurrent infection caused by the bacterium Mycobacterium tuberculosis. "The results of ROC showed that TYMP (AUC = 0.964), LAP3 (AUC = 0.914), ADGRL2 (AUC = 0.98), SIL1 (AUC = 0.936), LMO7 (AUC = 0.856), SULF1 (AUC = 0.96), ANXA3 (AUC = 0.798), and PACSIN3 (AUC = 0.747) had high accuracy in predicting tuberculosis." (PMID 39023413, 2024).
Usher syndrome (1 paper, 2025). A syndromic diseae characterized by the association of sensorineural deafness (usually congenital) with retinitis pigmentosa and progressive vision loss. "Several genes, such as IGHV1-69D, CTSH, and LMO7, exhibited significant upregulation in Usher syndrome, while others, including SLC3A2, ABLIM1, and CBS, were notably downregulated." (PMID 40723835, 2025).